LACTBL1 (lactamase beta like 1)
Gene: Protein-coding gene on chromosome 1 (22,953,043 to 22,972,866, reverse strand). Ensembl gene ENSG00000215906.
Subcellular location (Human Protein Atlas): Nuclear bodies
Genetic constraint (gnomAD): Loss-of-function variants: 30 observed, 32.58 expected, observed/expected ratio (o/e) 0.92, 90% interval 0.69 to 1.25. The upper end of that interval is the gene's LOEUF score, 1.25, which puts it in group 5 of 6, group 1 being the genes least tolerant of losing a copy. Missense variants: 706 observed, 690.22 expected, observed/expected ratio (o/e) 1.02, 90% interval 0.96 to 1.09. Synonymous variants: 358 observed, 324.71 expected, observed/expected ratio (o/e) 1.1, 90% interval 1.01 to 1.2.
Homologues: Orthologues: chimpanzee LACTBL1 (93% identical), macaque LACTBL1 (92% identical), pig LACTBL1 (87% identical), rabbit LACTBL1 (86% identical), dog LACTBL1 (86% identical), mouse Lactbl1 (81% identical), rat Lactbl1 (80% identical), tropical clawed frog lactbl1 (61% identical), zebrafish lactbl1b (57% identical), guinea pig LACTBL1 (56% identical). Paralogues in human: LACTB (16% identical).
Diseases named in the same sentence as LACTBL1 in open-access papers:
LACTBL1 is named in the same sentence as 1 disease in open-access papers, as found by Europe PMC text mining. Sharing a sentence is not in itself a finding about the gene and the disease. The quoted sentences say what the papers report.
kidney cancer (1 paper, 2023). Primary or metastatic malignant neoplasm involving the kidney. "For example, in patients with kidney cancer, higher expression of LACTBL1 was correlated with a decrease in survival rates." (PMID 37580380, 2023).